SIL1 (SIL1 nucleotide exchange factor)
Description:
Required for protein translocation and folding in the endoplasmic reticulum (ER). Functions as a nucleotide exchange factor for the ER lumenal chaperone HSPA5.
Synonyms: BAP; ULG5; MSS
Tractability: Small molecule: a structure with a bound ligand is known. Antibody: UniProt predicts a signal peptide or a membrane-spanning region. PROTAC: UniProt records ubiquitination sites on it; ubiquitination databases record sites on it; its protein half-life has been measured.
Gene: Protein-coding gene on chromosome 5 (138,946,720 to 139,293,557, reverse strand). Ensembl gene ENSG00000120725.
Subcellular location: Endoplasmic reticulum lumen
Gene Ontology:
Molecular function: adenyl-nucleotide exchange factor activity; identical protein binding; protein binding
Biological process: cotranslational protein targeting to membrane; intracellular protein transport; protein folding
Cellular component: endoplasmic reticulum; extracellular region; endoplasmic reticulum lumen
Genetic constraint (gnomAD): Loss-of-function variants: 40 observed, 50.91 expected, observed/expected ratio (o/e) 0.79, 90% interval 0.61 to 1.02. The upper end of that interval is the gene's LOEUF score, 1.02, which puts it in group 4 of 6, group 1 being the genes least tolerant of losing a copy. Missense variants: 500 observed, 593.16 expected, observed/expected ratio (o/e) 0.84, 90% interval 0.78 to 0.91. Synonymous variants: 253 observed, 256.67 expected, observed/expected ratio (o/e) 0.99, 90% interval 0.89 to 1.09.
Gene-disease validity (ClinGen):
ClinGen rates the evidence that SIL1 causes each of these diseases.
Marinesco-Sjogren syndrome (autosomal recessive): Definitive. Marinesco-Sjogren syndrome (MSS) belongs to the group of autosomal recessive cerebellar ataxias.
Homologues: Orthologues: chimpanzee SIL1 (99% identical), macaque SIL1 (96% identical), dog SIL1 (92% identical), pig SIL1 (89% identical), rabbit SIL1 (88% identical), guinea pig SIL1 (87% identical), mouse Sil1 (85% identical), rat Sil1 (82% identical), tropical clawed frog sil1 (50% identical), zebrafish sil1 (46% identical), Drosophila melanogaster Sil1 (26% identical). Paralogues in human: HSPBP1 (18% identical).